POSTN (periostin)
Diseases named in the same sentence as POSTN in open-access papers (continued):
Sharing a sentence is not in itself a finding about the gene and the disease.
prostate carcinoma (continued). "Increased cancer cell expression of periostin compared to normal glands was found during early stages of prostate cancer whereas in advanced stages stromal periostin expression prevailed." (PMID 20534149, 2010). "This is in contrast to our study of 418 prostate carcinomas where we find increased epithelial periostin expression positively correlated to grade and stage and increased stromal periostin positively correlated to grade." (PMID 20534149, 2010). "In total, strong epithelial periostin expression was detectable in 142 of 418 (34.0%) of prostate carcinomas and in 11 of 38 benign prostate glands (28.9%)." (PMID 20534149, 2010). "This immunohistochemical study describes the periostin protein expression pattern in prostate cancer and benign prostate tissue in a large patient cohort." (PMID 20534149, 2010). "Augmentation of both epithelial and stromal periostin in our cohort is a characteristic of the advanced and more aggressive prostate cancer cases." (PMID 20534149, 2010). "These expression characteristics and its proposed drugability make periostin a promising target for an individualized prostate cancer therapy." (PMID 20534149, 2010). "Here, we evaluated periostin expression in prostate cancer cells and peritumoural stroma immunohistochemically in two independent prostate cancer cohorts, including a training cohort (n = 93) and a test cohort (n = 325)." (PMID 20534149, 2010). "Our data demonstrate a significant association between periostin and pT-stage, Gleason grade and involvement of prognosis in two different prostate cancer cohorts, suggesting that EMT is of utmost importance for prostate cancer progression." (PMID 20534149, 2010). "Interestingly, the expression of periostin was suppressed using Twist shRNA in prostate cancer cell lines." (PMID 36224629, 2022). "Our findings indicate that targeting POSTN in prostate cancer cells as well as in osteoblast may be an effective treatment for PCa bone metastasis." (PMID 35087756, 2021). "POSTN has been also shown to induce EMT in prostate cancer cells." (PMID 29946533, 2018). "In addition, a Twist shRNA was also shown to be able to inhibit POSTN expression in prostate cancer cell lines." (PMID 29946533, 2018). "Several studies have demonstrated that POSTN expression is altered in prostate cancer." (PMID 29946533, 2018). "Nevertheless, POSTN expression in the stromal component of normal tissues was about twice as high as what was observed in the epithelial component of prostate cancer tissues (p=0.003), indicating that stromal cells mostly contribute to POSTN secretion both in normal and in neoplastic conditions." (PMID 23273263, 2012). "So far there is only a single report on periostin expression in prostate cancer." (PMID 20534149, 2010). "However, this also demonstrates that the prognostic value of periostin is limited in comparison to well established conventional prognosticators of prostate cancer and other potentially prognostic molecular markers." (PMID 20534149, 2010). "Our data indicate that periostin up-regulation is related to increased tumour aggressiveness in prostate cancer and might be a promising target for therapeutical interventions in primary and metastatic prostate cancer." (PMID 20534149, 2010). "In total, 142/418 prostate cancer cases expressed high levels of epithelial periostin." (PMID 20534149, 2010). "In this study, we provide evidence for periostin up-regulation during prostate cancer progression." (PMID 20534149, 2010). "Since periostin is often found to be highly expressed in tumor microenvironments, expression of periostin in the adult BM can help to establish a pre-metastatic niche for tumor cells with a predilection for metastasis formation in the BM, such as breast or prostate cancer cells." (PMID 34838648, 2022). "In this case, POSTN overexpression in PC3 and DU145 prostate cancer cells promoted cell proliferation, invasion, and migration." (PMID 29946533, 2018).
prostate carcinoma (continued). "We first found that TGF-β effectively induced periostin expression in U87-MG cells, in accordance with studies in PC3 and DU145 prostate cancer cell lines." (PMID 29774119, 2018). "The correlation between periostin expression and EMT has been observed in prostate cancer, through the downregulating of E-cadherin expression via Snail." (PMID 28977942, 2017). "Although our observation of negative correlations of the MVD with periostin level is in contrast to the results of this correlation in prostatic cancer, we hypothesize that in CRC, higher level of periostin is stimulated by hypoxia." (PMID 35056404, 2022). "In the present study, we investigated the expression level of periostin in the primary prostate cancer tissues, non-tumorous prostate tissues, benign prostatic hyperplasia, and prostate intraepithelial neoplasia." (PMID 25781169, 2015). "Sixty (18.5%) primary prostate cancer cases showed no epithelial periostin expression and 189 (58.2%) cases had an IRS equal to or below 3 (median 3)." (PMID 20534149, 2010). "Expression of periostin is an indicator of epithelial-mesenchymal transition in cancer but a detailed analysis of periostin expression in prostate cancer has not been conducted so far." (PMID 20534149, 2010).
heart failure (30 papers, 2013 to 2025). Inability of the heart to pump blood at an adequate rate to meet tissue metabolic requirements. "Previous studies indicated that POSTN is abundant in embryonic cardiac tissue, diabetic cardiomyopathy, the aging heart, and heart failure-associated fibrosis." (PMID 31167519, 2019). "Gene polymorphisms analysis in Chinese population showed that rs3829365 of the periostin gene was associated with susceptibility to, and severity of heart failure, suggesting a role of periostin in disease prediction and severity assessment." (PMID 24586384, 2014). "In heart failure patients, periostin distribution and expression has been associated with the amount of fibrotic tissue, suggesting that periostin may be a potential biomarker of cardiac remodeling in this setting." (PMID 36015225, 2022). "Furthermore Periostin expression is upregulated and associated with myocardial fibrosis in patients with heart failure and seems to play a role in various inflammatory settings." (PMID 25221676, 2014). "Therefore the increase of periostin expression and protein levels in c-jun-deficient hearts might contribute to heart failure." (PMID 24039904, 2013). "Periostin has been shown to correlate and contribute to cardiac remodeling and fibrosis in overloaded hearts and heart failure." (PMID 40843168, 2025). "Two research groups have reported that periostin-expressing fibroblasts in the heart play an important role in pathological cardiac fibrosis in heart failure." (PMID 38503742, 2024). "These previous findings suggest that the functional proteins in periostin-expressing fibroblasts are a potential molecular target for a pharmacological therapy for heart failure." (PMID 38503742, 2024). "POSTN(+)CD68(+)COL1A1(+) cells were clearly observed in human tissues from patients with heart failure, indicating the presence of the MMT in human hearts." (PMID 39261656, 2024). "Up-regulated differentially expressed genes (DEGs) of different datasets showed that the heart failure groups expressed significantly genes involved in cardiac fibrosis, including POSTN and DES." (PMID 36805782, 2023). "Several subpopulations of fibroblasts such as fibroblast-THBS4, fibroblast-FN1, fibroblast-POSTN were also found in human heart increasing with heart failure, which is consistent with our results in mice." (PMID 36805782, 2023). "Consistently with the mouse heart data, immunofluorescence staining data showed that the expression of VIM, PDGFRA and POSTN were significantly increased in the heart failure group compared with the normal heart." (PMID 36805782, 2023). "Consistent with above data, cluster 1 (subtypes with high expression of extracellular matrix protein including DDR2, THBS4, FN1, POSTN) at heart failure which involved in ECM organization, extracellular structure organization." (PMID 36805782, 2023). "During heart failure, the pattern of desmin, vimentin, periostin and caspase-3 expression alters in the left atrium, regardless of the cause." (PMID 27980728, 2016). "Top candidates are significantly involved in cell fate specification and differentiation, and include heart failure markers such as periostin, as well as potential new targets for heart regeneration." (PMID 25280539, 2014). "Among them, periostin, which regulates cardiac homeostasis, is a well-known marker of heart failure." (PMID 25280539, 2014). "Additionally, this tool effectively predicted connective tissue growth factor (CTGF) and periostin (POSTN) as direct targets of miR-30a-5p in heart failure conditions." (PMID 40699815, 2025). "Furthermore, we observed the proportion of markers associated with fibroblasts (VIM, POSTN, DDR2, THBS4, COL1A1, COL1A2, FN1) were significantly higher in heart failure than the control group in the human data, which were consistent with that in mice." (PMID 36805782, 2023).
heart failure (continued). "Periostin deposition has also been demonstrated to be involved in repair after vascular injury, and there is evidence that periostin insufficiency may contribute to valvular heart disease, heart failure, and atherosclerosis." (PMID 24146092, 2014). "Indeed, periostin (POSTN) was the most upregulated gene relative to 3DV hPSC-ECs, and although low-level expression of this complex, multifunctional protein is observed within VECs, it is upregulated during heart failure and can induce the EndMT cascade." (PMID 38775849, 2024). "A systems transcriptomic study identified fibronectin-1 (FN1) and periostin (POSTN) as hub genes during CRS progression in rats, and importantly, these were found to be highly expressed across numerous human heart failure and kidney disease datasets as well." (PMID 41300756, 2025). "Similar to SysHF HLHS fibroblasts, RVF fibroblasts displayed enriched levels of POSTN, FAP, FOS, and JUN, consistent with a preserved activated fibroblast population observed across human heart failure etiologies." (PMID 40502733, 2025). "Our studies focused on periostin, a unique and major contributor of ECM remodelling in the heart; and galectin-3, an established biomarker of heart failure that binds ECM components and transduces or modulates fibrogenic signalling cascades." (PMID 36968272, 2023). "Consistent with our mouse data, cluster 6 (subtypes with high expression of extracellular matrix protein including POSTN, THBS4) at heart failure which showed elevated capacity of ECM organization, extracellular structure organization." (PMID 36805782, 2023). "The distribution and expression patterns of periostin, which correlated with the degree of myocardial fibrosis, could serve as a potential biomarker for cardiac remodeling in patients with HCM heart failure." (PMID 40843168, 2025). "We stained heart sections from healthy people and patients with heart failure (with a history of hypertension and hyperlipidemia) using immunofluorescence and found that CD34 costaining for DDR2, POSTN, and FABP4 was greater in the heart failure group than in the control group." (PMID 39198543, 2024). "In addition, as shown in the volcano plot, the levels of active fibroblast markers (POSTN, THBS4, CILP, and FN1) were increased in the heart failure group." (PMID 39198543, 2024). "Functionally, in myocardial tissue, RASGRP1 mediates angiotensin П-induced phosphorylation of p38 MAPK and expression of periostin protein, inhibiting the expression of RASGRP1 in the heart may help improve heart failure." (PMID 38730425, 2024). "In addition, immunofluorescence staining demonstrated elevated expression levels of fibroblast markers (such as POSTN and PDGFRA) and FABP4+ fibroblasts (FABP4 + POSTN+ and FABP4 + PDGFRA+) in the heart failure group compared to those in the control group." (PMID 39198543, 2024). "In addition, we found that active fibroblast markers (POSTN, THBS4, CILP, and FN1) were significantly elevated in the heart failure group." (PMID 39198543, 2024). "Among other extracellular matrix genes, upregulation of periostin, connective tissue growth factor (Ctgf) and WNT1 inducible signaling pathway protein 1 (Wisp1) were most interesting, since their involvement in triggering myocardial fibrosis and heart failure has been previously established." (PMID 24039904, 2013).
nasal polyps (29 papers, 2015 to 2026). "Human nasal epithelial cells (HNECs) and fibroblasts (HNFs) derived from nasal polyps were used to investigate periostin induction in response to Th2 and other inflammatory cytokines." (PMID 40607434, 2025). "Periostin concentrations in nasal polyp homogenates of eosCRSwNP patients was also found to correlate positively with Lund-Mackay CT scoring." (PMID 36832203, 2023). "The expression of IL-5, POSTN and IL-33 mRNA was determined in sinonasal mucosal samples and in nasal polyp tissue by real-time PCR." (PMID 35752781, 2022). "Among patients of CRS with nasal polyposis (CRSwNP), expression of the periostin gene seemed to be notably upregulated in nasal polyps than in normal sinus mucosa." (PMID 36611844, 2022). "Glucocorticoids ameliorate periostin-induced tissue remodeling in chronic rhinosinusitis with nasal polyps." (PMID 32954441, 2021). "We also found higher levels of periostin in nasal polyps compared with the controls and higher levels of tenascin C in nasal polyps compared with CRSsNP and the controls." (PMID 34504680, 2021). "Periostin is a confirmed novel biomarker for the formation of nasal polyps and tenascin C is an indicator of inflammation." (PMID 34504680, 2021). "A significant correlation was seen between the number of eosinophils and the mRNA expression levels of 15-LOX-1 and periostin in nasal polyps." (PMID 33218117, 2020). "Eosinophil counts of nasal polyps showed a significant positive correlation with sputum periostin and FeNO levels." (PMID 32015784, 2020). "The increase of periostin was prominent when patients had nasal polyps (NPs) with olfactory dysfunction." (PMID 32015784, 2020). "AE in chronic rhinosinusitis with nasal polyps (CRSwNP) was associated with increased expression of mucus cytokines including myeloperoxidase (percentage increase [PI] = 101%), IL-5 (PI = 125%), and IL-6 (PI = 162%) and could be predicted by the increasing mucus cystatin and periostin." (PMID 32811568, 2020). "An analysis of the expression level indicates the participation of POSTN and IL-4 in the development of chronic rhinosinusitis with nasal polyps in patients with atopy." (PMID 25573836, 2015). "The upregulation of POSTN in these conditions points to its potential involvement in the pathophysiological processes, possibly mediating between inflammatory responses and tissue remodeling outcomes such as nasal polyp formation." (PMID 39728072, 2024). "This dual role could explain the elevation of periostin in ACPs, which implies an interplay between inflammatory and remodeling pathways in nasal polyp subtypes." (PMID 39728072, 2024). "The pathophysiology behind how Dupilumab resolved CRSwNP and EOM may involve periostin expression in the granulation tissue of nasal polyps and the middle ear." (PMID 39595049, 2024). "Additionally, Angiotensin II blockers show a positive effect in nasal polyposis, possibly, through inhibition of periostin." (PMID 37206761, 2023). "Thus, we investigated the roles of periostin and tenascin C in promoting the expression of MMPs via fibroblasts and the nasal epithelium in nasal polyps." (PMID 34504680, 2021). "In this context, we speculated that periostin and tenascin C might be able to regulate the expression of these MMPs within nasal polyps." (PMID 34504680, 2021). "Additionally, periostin and tenascin C have been reported to stimulate the expression of MMPs beyond nasal polyps." (PMID 34504680, 2021). "Periostin and tenascin C might be involved in the remodeling of nasal polyps by regulating the expression of different MMPs in epithelial cells and fibroblasts." (PMID 34504680, 2021). "Genome-wide transcription studies demonstrated that nasal polyps showed remarkedly higher gene expression of periostin as compared with normal sinus mucosa and lately, real-time quantitative reserve transcription polypmerase chain reaction (PCR) and immunohistochemistry (IHC) also confirmed this." (PMID 32954441, 2021).